RNU6-726P (RNA, U6 small nuclear 726, pseudogene)
Gene: Small nuclear RNA gene on chromosome 3 (131,092,821 to 131,092,927, reverse strand). Ensembl gene ENSG00000201550.
Homologues: Orthologues: chimpanzee U6 (96% identical), macaque U6 (92% identical), rat U6 (80% identical), rabbit U6 (79% identical), rabbit U6 (67% identical). Paralogues in human: RNU6-11P (91% identical), RNU6-37P (91% identical), RNU6-1175P (90% identical), RNU6-12P (90% identical), RNU6-13P (90% identical), RNU6-16P (90% identical), RNU6-19P (90% identical), RNU6-32P (90% identical), RNU6-1 (89% identical), RNU6-1083P (89% identical), RNU6-1316P (89% identical), RNU6-17P (89% identical), and 1289 more.